HGF (hepatocyte growth factor)
Diseases named in the same sentence as HGF in open-access papers (continued):
Sharing a sentence is not in itself a finding about the gene and the disease.
tumor (continued). "This candidate HGF variant was characterized and evaluated for its ability to mediate c-MET activation and regulate PDX GBM cell growth, motility and invasive potential in vitro and tumor burden in intracranial xenografts in mice." (PMID 37162666, 2023). "Correlation between tumor and plasma HGF expression and the prognostic values were analyzed." (PMID 37828456, 2023). "In HNSCC, HGF induces glycolysis, which facilitates the secretion of tumor-derived lactate." (PMID 36980785, 2023). "This correlation can be attributed to several factors, including the immunosuppressive effects of neutrophils, their ability to promote tumor growth, and their facilitation of tumor cell migration and invasion through the release of factors such as hepatocyte growth factor (HGF)." (PMID 37533853, 2023). "Tumor specimen were analyzed for HGF expression by immunohistochemistry." (PMID 37170275, 2023). "In vitro, HGF increases tumor growth only in anchorage-independent conditions." (PMID 37381723, 2023). "Met-Hepatocyte growth factor (HGF) axis is essential in tumor progression and drug sensitivity." (PMID 37860119, 2023). "Serine proteases can degrade extracellular matrix proteins as well as growth factors such as epidermal growth factor (EGF), fibroblast growth factor-2 (FGF-2) and hepatocyte growth factor/scatter factor (HGF-SF) and are involved in tumour cell invasion, angiogenesis and metastasis." (PMID 37055381, 2023). "In this way, we exclusively evaluated the relevance of the HGF/MET axis in prompting cell-autonomous activities (MET signaling in tumor microenvironment cells is maintained intact) independently of their intrinsic ability to proliferate (that is sustained by different oncogenic drivers)." (PMID 37345079, 2023). "Furthermore, using an independent cohort of 71 SCLC patients at our institute, we identified HGF expression in tumor tissue and paired plasma and also explored the potential use of plasma HGF in predicting metastasis and prognosis." (PMID 37828456, 2023). "We achieve this by summarizing the intricate crosstalk between the primary c-MET and Hh pathways within tumor cells, the downstream effects of Hh pathway activation on the TME and CAFs, and the role of SHH and HGF serves as a bridge in the context of stromal-tumor interactions." (PMID 37919751, 2023). "Hepatocyte growth factor is a cytokine secreted by the stromal cells in the tumor microenvironment." (PMID 36789987, 2023). "Hepatocyte growth factor (HGF) is a peptide-containing multifunctional cytokine, which is overexpressed and/or activated in multiple malignancies and is reported to be associated with tumor development and inferior survival." (PMID 37828456, 2023). "Additionally, we have explored the role of Hh and HGF as mediators in the interaction between tumor cells and the stromal matrix." (PMID 37919751, 2023). "CAFs typically secrete CXCL12, TGF-β, LOXL2, HGF, and IL-22 to promote tumor progression." (PMID 36992704, 2023). "Our findings suggest that under the inhibitory effect of an EGFR TKI, HGF-mediated PIP3 activation may bypass EGFR-mediated PIP3 activation, an observation further supported by elevated HGF expression in tumors with higher tumor-stroma interactions." (PMID 36647832, 2023). "Macrophages secrete HGF accompanied by a significant increase in M2 over M1 type macrophages, which has been shown in vitro and in vivo to significantly increase resistance to sorafenib by maintaining tumor growth." (PMID 36769116, 2023). "HGF‐producing and expressing cells engage in crosstalk within the TME, including between the stromal and epithelial components, as well as among stromal cells like tumor‐associated macrophages and neutrophils." (PMID 38077251, 2023). "In HCC, HGF is enriched in primary CAFs and can accelerate tumor progression and dissemination." (PMID 36708970, 2023).
tumor (continued). "Indeed, upregulation in plasma and plasma HGF, soluble MET, and phosphor-MET have been associated with primary and distant tumor progression, resistance to therapy, and overall poorer outcomes." (PMID 38067195, 2023). "The tumor-activated HS-5 is enriched in soluble uPAR (SuPAR), IL-6, and hepatocyte growth factor (HGF), which might be responsible for chemoresistance induction." (PMID 37175439, 2023). "Immunohistochemical (IHC) staining and integrated optical density (IOD) also indicated that p-MET and HGF expression in the tumor tissues of the mice decreased in a dose-dependent manner after treatment with foretinib; p-MET and HGF protein expressions are represented by the brown staining." (PMID 36614199, 2023). "Upregulated HGF expression in tumor was observed in some solid tumors." (PMID 37828456, 2023). "As a conclusion to this study, it can be stated that the significant relationship between the serum HGF level and systemic inflammation markers in this study is thought to be the reflection of the relationship between HGF and inflammation in the tumor microenvironment to the peripheral blood." (PMID 36789987, 2023). "As such, the broad depletion of stromal cells by FAP-CAR T cells may induce the reduction of tumor-enhancing growth factors including HGF and c-Met, thus limiting the proliferation and invasiveness of cancer cells." (PMID 37607999, 2023). "Additionally, HGF secreted by adjacent CAFs significantly enhances the stemness of tumor cells and regulates their metabolism." (PMID 37919751, 2023). "Inhibiting the HGF/c-Met pathway reduced HNSCC tumor growth." (PMID 36980785, 2023). "Treatment with foretinib can significantly inhibit the expression of p-MET and HGF in the tumor." (PMID 36614199, 2023). "Moreover, the cytokines produced by CAFs are also involved in tumor resistance to targeted therapies, such as fibroblasts that produce HGF lead to resistance of lung cancer cells to epidermal growth factor receptor tyrosine kinase inhibitors (EGFR-TKIs)." (PMID 37666813, 2023). "An adenovirus armed with CD40L and 4‐1BBL; activates CD40 and 4‐1BB pathways; Decrease the tumor growth factors (including Spp‐1, Gal‐3, HGF, TGFβ, and collagen type I); Increase cytokines and chemokines, and such DCs potently expanded both antigen‐specific T cells and NK cells." (PMID 36880311, 2023). "Meanwhile, several preclinical studies also revealed that incomplete ablation could promote tumor progression and tumor angiogenesis via the IL-6/HGF/c-Met pathway, the HGF/c-Met/STAT3 pathway, and the upregulation of VEGF." (PMID 36831664, 2023). "Further, the liver synthesized growth factors IGF-1 and HGF/SF are affected by levels of exercise, stress, nutrition and BMI, and may contribute to metastatic progression and tumor cell homing to the liver." (PMID 36973672, 2023). "Similarly, human placenta-derived MSCs transduced by the HGF antagonist NK4 can inhibit tumor cell growth by inducing apoptosis." (PMID 37666813, 2023). "In addition, HGF is a kind of stromal cytokine that can promote tumor angiogenesis by stimulating vascular endothelial cell migration and activating protein kinase B and ERK." (PMID 36874003, 2023). "There are accumulating data suggesting that HIF1α and HGF may act as pro-tumour factor while TIMP-2 is an anti-cancer regulator." (PMID 35953652, 2023). "HGF, as a promoter of cell proliferation, could potentially drive tumor-like hyperproliferation of the transplanted hiPSC-NS/PCs." (PMID 37845736, 2023). "Moreover, MET exon 14 depletion by employing CRISPR editing technology leads to the enhanced cell migration, tumor invasion, and tumor metastasis through the HGF/MET axis in NSCLC." (PMID 38188023, 2023). "Additionally, epigenome screening identified serine protease inhibitor kunitz-type 2 (SPINT2–an inhibitor of HGF activation) as a potential tumor suppressor gene in MB." (PMID 36034555, 2022).
tumor (continued). "Furthermore, TANs secrete HGF and high levels of prokineticin 2 (Bv8), a potent mitogenic factor for endothelial cells and the main angiogenic factor in neutrophil-dependent tumor angiogenesis." (PMID 36555469, 2022). "Adipocytes and their precursor cells can influence tumor behavior via various hormones, growth factors, and cytokines known as adipokines including leptin, adiponectin, IL-6, hepatocyte growth factor, autotaxin, and TNF-alpha although their exact mechanism of action has not been established." (PMID 34532758, 2022). "High level of HGF in the tumour microenvironment favouring paracrine tumour-stroma crosstalk, c-Met overexpression, ligand-independent activation, exon 14 deletion and less often kinase domain mutations are well documented mechanisms utilised by the tumour cells." (PMID 36330337, 2022). "Previous studies demonstrated that MACC1 can regulate the expression of the oncogene c-MET and promote epithelial-mesenchymal transformation, migration, proliferation, angiogenesis, and drug resistance in various tumor cells through the HGF/c-MET/MAPK and HGF/c-MET/AKT pathways." (PMID 35874635, 2022). "Gaurav Kumar reported that c-Met inhibitor could block HGF/c-Met pathway which mediated distant subcutaneous tumor growth after RFA of normal liver." (PMID 35710408, 2022). "There is ample evidence in the literature reviewed above to suggest that targeting the HGF/c-MET pathway could be an effective anti-cancer strategy across a range of tumor types." (PMID 36034555, 2022). "In previous studies, the HGF/c-Met signaling pathway is a key factor in tumor progression." (PMID 35242498, 2022). "In addition, the two nanobodies were evaluated for their therapeutic effect, due to their anti‐HGF activity, resulting in tumor growth inhibition after treatment with 100 mg intraperitoneal injections, 3 injections per week over 5 weeks." (PMID 35292998, 2022). "Additionally, it has been reported that the expression of SDF-1 and HGF in cancers supports tumor cell chemotaxis and invasiveness." (PMID 34874922, 2022). "MACC1 binds to the positive feedback of the c-Met promoter region to activate the HGF/c-Met pathway, upregulates the expression of downstream target cyclin D1, and promotes tumor cell proliferation, invasion, metastasis, and epithelial mesenchymal transformation (EMT)." (PMID 35242498, 2022). "HGF is believed to promote the various types of tumor formation and progression and may contribute to the either primary or acquired mechanism of resistance to cancer immunotherapy." (PMID 35568859, 2022). "Factors like SDF-1 (stromal derived factor-1), HGF (hepatocyte growth factor/scatter factor), VEGF (vascular/endothelial growth factor) secreted by stromal cells or tumor-associated macrophages (TAM) attract GC cells through the CXCR4, CXCR7, c-Met and KDR receptors." (PMID 35328253, 2022). "Also, translocation of EGFR promoted tumor invasion and metastasis by hindering miR-26a/b, thus, up-regulating the expression of hepatocyte growth factor (HGF)." (PMID 35173726, 2022). "Thus, the unique HGF-dependent ∆14 oncogenic activity suggests consideration of HGF in the tumour microenvironment to select patients for clinical trials." (PMID 35636967, 2022). "Hepatocyte growth factor (HGF) contribute to tumor development through its specific receptor MET." (PMID 35127296, 2022). "Moreover, c-MET has emerged as a key target for modulating the c-MET/HGF axis for tumor therapy, showing promising therapeutic potential for c-MET-positive tumors." (PMID 36233320, 2022). "Finally, the expression of IL-15 and HGF genes, known to promote tumor cell survival, was higher at diagnosis than in paired relapse samples." (PMID 36230815, 2022). "c-Met could not only bind HGF and then activate downstream signals to promote tumor progression, but also activate downstream oncogenic pathways through molecular interactions with other oncogenic molecules." (PMID 35978812, 2022).
tumor (continued). "Treatment with a mAb against HGF in this model improved overall survival, though the inhibition of tumor growth was incomplete, leading the authors to hypothesize that dual inhibition of both SHH and HGF would be more effective." (PMID 36034555, 2022). "The hepatocyte growth factor (HGF) could promote tumor progression by activating downstream pathways, such as phosphatidylinositol 3-kinase-AKT, RAS-mitogen-activated protein kinase, and vascular endothelial growth factor (VEGF) signaling." (PMID 35155421, 2022). "Some of the mediators that are recognized include tumor necrosis factor (TNF), vascular endothelial growth factor (VEGF), interleukin-6 (IL6), which has a key role as a growth factor for tumor cells, hepatocyte growth factor (HGF), and transforming growth factor beta (TGF-β)." (PMID 36362398, 2022). "Upon binding to its ligand hepatocyte growth factor (HGF), the cMET signaling pathway controls tumor cell survival and metastasis in part via activation of the PIK3CA/AKT/mTOR pathway as well as contributing to antiangiogenic therapeutic resistance via upregulation of MET expression." (PMID 36969746, 2022). "The HGF/c-Met pathway in lipid rafts plays a significant role in the tumor microenvironment." (PMID 36284313, 2022). "Moreover, HGF/c-MET signaling is also involved in the regulation of tumor microenvironment, immune infiltration, and immune response." (PMID 35558557, 2022). "HGF may be part of a comprehensive panel that reflects the biological and clinical behaviors of each tumor." (PMID 34997350, 2022). "Hepatocyte growth factor (HGF) is a potent inducer of tumor growth and the formation of metastasis." (PMID 35626756, 2022). "Increasing evidence showed that activated CAFs could regulate tumor cell invasion and growth by secreting soluble factors (exosomes, HGF and GAS6) and depleting metabolic factors (lactate, amino acid, alanine, and aspartate)." (PMID 36389798, 2022). "c-Met-β1, c-Met-α3, and c-Met-α6β4 association was shown to occur in a range of tumour cells in the absence of HGF." (PMID 36330337, 2022). "HGF/c-Met signaling, which is localized in lipid rafts, correlates with the tumor microenvironment." (PMID 36284313, 2022). "One may argue that the HGF/SF-MET pathway is strongly involved in tumour progression and metastasis spreading." (PMID 35905995, 2022). "Platelets can secrete transforming growth factor, interleukin, hepatocyte growth factor, and other cytokines that interact with the tumor microenvironment, which can induce the immune escape of the tumor cells and promote the formation of tumor neovascularization." (PMID 36005195, 2022). "Anti-tumor activity of neutrophils is regulated via various factors, such as the release of nitric oxide induced by hepatocyte growth factor (HGF) through binding to tyrosine-protein kinase MET, the generation of hydrogen peroxide (H2O2), and the secretion of the tumor necrosis factor TNF-α." (PMID 35267547, 2022). "Overall, with this bidimensional analysis we could show that tumor samples were well characterized by high secretions of IL-16, HGF, the TGF-β1, 2 and 3, SCF, FGF-2 and VEGF, and low secretions of CCL8 and Leptin." (PMID 36539890, 2022). "Since EpCAM and HGF/c-Met are involved in important signaling pathways in various cancers, the purpose of this study is to elucidate the interplay between these molecules, tumor microenvironment, and intracellular pathways." (PMID 35986321, 2022). "Therefore, c-Met is a promising target for tumor and several HGF/c-Met targeting inhibitors and antibodies have been developed." (PMID 35710408, 2022). "To confirm whether E7050 exerts potent anti-tumor effect by targeting c-Met-mediated signaling pathways, we next detected the expression of c-Met and its downstream effectors in HGF-stimulated MES-SA/Dx5 cells." (PMID 36499211, 2022).
tumor (continued). "Interestingly, it is known that the expression of CD44 isoforms containing exon v6 is a prerequisite for c-Met activation by its ligand HGF in several tumor cells and in primary cells." (PMID 35488271, 2022). "In tumor cells lying between 500 μm and 1000 μm from blood vessels, migration is not directed towards the blood vessels but is toward macrophages which draws the tumor cell macrophage pairs into the HGF gradient." (PMID 35565297, 2022). "We could also show co-localization of CD44 and HGF in the parental tumor tissues, validating the relevance of predicted interactions from our co-culture model in the in vivo context." (PMID 36273171, 2022). "Cancer-associated fibroblast-derived HGF can activate c-Met/PI3K/Akt and glucose-regulated protein 78 (GRP78) signaling pathways to promote tumor cell proliferation and induce drug resistance in tumor cells." (PMID 35684449, 2022). "Furthermore, HGF/MET signaling has emerged as a critical player not only in the tumor itself but also in the tumor microenvironment." (PMID 34771620, 2021). "Therefore, to achieve a successful tumor diagnosis or prognosis assessment more comprehensively, systematic integration of the HGF/c-MET pathway and immune-related pathways are needed for further analysis." (PMID 34261467, 2021). "We systematically analyzed 11 different cancers, including expression correlation, immune infiltration, tumor diagnosis and survival prognosis from HGF/c-MET pathway and immune regulation, two biological mechanisms having received extensive attention in cancer analysis." (PMID 34261467, 2021). "As in the HGF-cMet axis, the activation of such pro-survival pathways protect against liver injury and promote liver regeneration, but their failure might promote tumor development in the presence of undetectable micrometastases." (PMID 34572344, 2021). "FAK-mediated signaling was induced by numerous microenvironmental inputs and plays a central role in tumor-associated EMT and epithelial cells extrusion, migration, and response to the transforming growth factorβ (TGFβ) and the hepatocyte growth factor (HGF), as often demonstrated on MDCK cells." (PMID 34631854, 2021). "Compared with Wt mice, HGF-Tg mice have lower tumor incidence, number, volume, and lesion grade." (PMID 34970484, 2021). "HGF also plays a crucial role in the development and progression of many tumor cells." (PMID 34930225, 2021). "However, TACE or HAIC induce ischemic conditions in tumor tissues, which upregulates hypoxia-inducible factor 1-α expression, leading to increased production of VEGF, FGF, HGF, and other angiogenic factors in tumor tissues." (PMID 33466496, 2021). "In this study, we systematically analyzed 11 different cancers, including expression correlation, immune infiltration, tumor diagnosis and survival prognosis from HGF/c-MET pathway and immune regulation, two biological mechanisms that have received extensive attention in cancer analysis." (PMID 34261467, 2021). "In addition, MET/HGF signaling protects tumour cells from DNA damage by activating the PI3K/AKT pathway." (PMID 34761497, 2021). "Interestingly, siRNA against HGF packed in exosomes has been described to be transported into tumor cells metastasizing peritoneum, suppressing proliferation and migration." (PMID 34768926, 2021). "HGF/MET signaling can recruit neutrophils to the tumor microenvironment from the bone marrow." (PMID 34771620, 2021). "In addition, OvCA-produced HGF is known to transform the peritoneum via MMT into a more suitable niche for subsequent tumor invasion." (PMID 34768926, 2021). "Curcumin has been shown to inhibit HGF-induced tumor metastasis and invasion." (PMID 34408780, 2021). "Abnormally activated HGF/c-Met signaling in OSCC can promote the development of tumor cells." (PMID 34970484, 2021). "Therefore, the overactive HGF-c-Met axis, induced by CAFs upon radiotherapy treatment, supports tumor progression." (PMID 33673405, 2021).